RN7SL371P (RNA, 7SL, cytoplasmic 371, pseudogene)
Gene: Miscellaneous RNA gene on chromosome 1 (30,918,469 to 30,918,735, reverse strand). Ensembl gene ENSG00000266210.
Homologues: Paralogues in human: RN7SL96P (84% identical), Metazoa_SRP (84% identical), RN7SL123P (83% identical), RN7SL190P (83% identical), RN7SL163P (83% identical), RN7SL488P (83% identical), RN7SL510P (83% identical), RN7SL391P (82% identical), Metazoa_SRP (82% identical), RN7SL134P (82% identical), RN7SL774P (82% identical), RN7SL596P (82% identical), and 708 more.